IL4 (interleukin 4)
Diseases named in the same sentence as IL4 in open-access papers (continued):
Sharing a sentence is not in itself a finding about the gene and the disease.
infection (continued). "Plasma levels of IL-4, IL-7, and IL-15 were similar at acute infection and 3 months but declined at later time points, suggesting a slow recovery of T-cell-related perturbations within 12 months." (PMID 37310006, 2023). "Other serum cytokines measured were either unchanged during infection (CCL2) or below the limit of detection (IL-4, IL-1β and IL-10)." (PMID 37837930, 2023). "Infection with S. mansoni in untreated and alum-administered mice elicited increase in serum IL-4, IL-17, and IFN-γ, compared to naïve mice." (PMID 36920999, 2023). "We scored for IFN-γ, IL-12 p70, IL-1 β, TNF-α, IL-10, and IL-4 in their culture supernatants upon infection." (PMID 37928551, 2023). "Two analytes that showed little change during infection (and were therefore observed contributing to component factor 3) were IL-4 and IL-17." (PMID 37376607, 2023). "Depletion of CD4+ T cells, IL-10, or IL-4 before infection or vaccination ameliorated disease severity but consequently resulted in prolonged viral shedding." (PMID 37896776, 2023). "In the current study, T. canis infection induced a predominant decrease in IL-12 and IFN-γ levels and an increase in IL-4 along the course of the infection." (PMID 37874393, 2023). "Leukocytes play a fundamental role in the healing of injuries due to the anti-infection action and immunological regulation through the secretion of immune cytokines, such as interleukin (IL)-1β, IL-4 and IL-6, and tumor necrosis factor alpha (TNF-α)." (PMID 37330965, 2023). "In contrast, infection increased the concentration of IL-4 in the group treated with letrozole + testosterone; the increase in this group was dependent on testosterone concentration." (PMID 37384220, 2023). "iNOS mRNA and protein expression increased after IFNγ pre- and post-stimulation conditions upon infection with S.tm as compared to the uninfected control, whereas IL-4 under pre- and post-stimulation conditions even reduced it below control conditions." (PMID 37190073, 2023). "From D4 to D8, IFN-γ/IL-4 ratio increased almost 250%, indicating a type 1-skewed immunity, especially at severe stages of infection." (PMID 37146079, 2023). "Treated animals showed an increase of IFN-γ that was significant on days 21 and 28, while IL-4 shows a significant decrease on day 28 post-infection." (PMID 37284503, 2023). "Our results support that the cytokine responses after short induction by IL-4/IL-13 can already interfere with TJ development which, in turn, correlates with enhanced infection efficiency, suggesting that the Th2 cytokines can target the TJs rather early." (PMID 37289055, 2023). "This phenotype was linked to a population of virtual memory CD8+ T (CD8+ TVM) cells that expanded upon infection with the helminth via IL-4 and IL-4Rα signals." (PMID 37789420, 2023). "On day 5 PI, GATA3 mRNA and IL4 significantly increased after the infection compared to the control." (PMID 37593762, 2023). "In accordance with this theory, we discovered that Th2-type cytokines (IL-4 and IL-10) were notably increased in response to RHΔompdcΔuprt infection to balance the high production of Th1 cytokines." (PMID 37322556, 2023). "The functional consequences of early IL-4 production during L. major infection are diverse, depending on the time point of infection, the analyzed tissue, the studied mouse strain and the used parasite strain." (PMID 35894051, 2022). "The increase in CD4+IFNγ+ T cells and the decrease in CD4+IL-4+ T cells observed at the site of infection correlated with decreased parasite burden in the lesion of Mrp8;Metfl/fl mice." (PMID 35041723, 2022). "gondii antibodies and production of IFN-gamma and interleukin-4, which significantly prolonged the survival time after challenge infection with the T. gondii RH virulent strain." (PMID 36562441, 2022).
infection (continued). "The results, taken together, show that ex vivo infection with HSV-1 revealed successful viral penetration in IL-4/IL-13-stimulated skin, supporting that the virus can gain access via the external skin surface due to the Th2 cytokine-induced modifications." (PMID 35969080, 2022). "Cytokines transcriptional trends revealed an immunosuppressive response during early infection stages, with decreased expression of some cytokines, such as IL-12, IL-4, IL-5, IL-1, IL-18, and IL-15, at 2 dpi, 4 dpi, or both compared to control." (PMID 36187827, 2022). "Conversely, anti-inflammatory cytokines, such as IL-4, IL-5, IL-10 and IL-13, among others, seem to act to regulate the Th1-type response and favoring the development of infection." (PMID 35891310, 2022). "In hepatic iNKT cells IL-13 production during infection was linked to GATA-3+T-bet+ CD4+ and CD4- subsets while IL-4 and IFN-γ was produced by GATA-3+T-bet+ as well as GATA-3-Tbet+/- cells." (PMID 36159876, 2022). "Strikingly, 24 h after infection, IL-4/13 or TJDP treatment of N/TERT2G increased the viral titer by 48- and 47-fold, respectively, compared to media control." (PMID 35456017, 2022). "According to literatures, in C. sinensis infected mice, IL-4 production by splenocytes increased (> threefold) until 2–4 weeks post-infection, but declined thereafter." (PMID 36083861, 2022). "Local administration or expression of IL-4 enhanced the pulmonary clearance of Pseudomonas aeruginosa in vivo and decreased mortality following infection." (PMID 35356501, 2022). "The infection results in the differentiation of Th2 cells releasing interleukin-4 and IL-13 along with strong B cells responses primarily characterized by IgG1 production." (PMID 35690651, 2022). "The evaluations of cytokine mRNA expression indicated that, both the Th1 (IFN-γ, TNF-α, IL-12) and the Th2 (IL-4 and IL-10) types of cytokines were differentially upregulated during the early stage of infection." (PMID 35215986, 2022). "Corroborating the previous analysis, IL4 rs2070874*T and IFNG rs2069727*G were significantly associated with infection in a logistic regression model after adjusting for the confounders of age, sex and village." (PMID 35759449, 2022). "In the lungs, both IL-4 and IL-10 were significantly induced following infection with smooth Brucella spp., but levels were significantly lower with secondary compared to primary infection." (PMID 36032120, 2022). "Until the 10th day after infection, IL-4 and IL-5 were slightly recovered after hitting the low point." (PMID 35878385, 2022). "Intriguingly, after ex vivo infection of interleukin-4 (IL-4)/IL-13-treated skin, we observed infected cells supporting that Th2 responses already enabled the virus to overcome the protective skin barrier and gain access to its receptors to initiate infection." (PMID 35969080, 2022). "Depletion of ILC2s results in a failure to expel Nippostrongylus brasiliensis, and impairs IL-4-driven differentiation of Th2 CD4+ T cells following infection with Heligmosomoides bakeri." (PMID 36238293, 2022). "Ultimately, failure to adequately respond to IL-6 and IL-4 resulted in increased levels of M1 macrophage marker expression in vitro and exacerbated lung inflammation upon infection with Nippostrongylus brasiliensis in vivo." (PMID 34420044, 2022). "Another mechanism of IL-18 stimulation of the Th2 immune response was demonstrated using an animal model of Leishmania infection, a major infection which is characterized by increased serum level of IL-4." (PMID 35369454, 2022). "Otherwise, TCTs in M(IFN-γ) COI and G were higher than the same infection at M0 or M(IL-4), respectively." (PMID 36389843, 2022). "On the fifth day, the ratio of interferon-γ(IFN-γ)/interleukin-4(IL-4) increased, but it decreased during 9-16 days indicating that the helper T lymphocyte 1 (Th1) cells played a major role at the initial stage of infection and Th2 cells at the later stage." (PMID 35912246, 2022).
infection (continued). "This is why high concentrations of IL‐4 appear and produce effects in the later stages of infection." (PMID 36169259, 2022). "We also found that in splenic T cells of WT mice, infection obviously upregulated Th2 cytokines such as IL-4, IL-10, and IL-13." (PMID 35666747, 2022). "The analysis of IL-4 secretion confirmed the success of NF-κB sensing IL-4 over-expressing lentiviral vectors infection." (PMID 36046680, 2022). "Notably, mice in Th1 polarised settings (including IL-4 deficient or IL-10/IL-4 double-deficient mice) exhibit rapid weight loss at the onset of egg production, elevated expression of proinflammatory Th1 cytokines and mediators, and high levels of mortality between wks 8-10 of infection." (PMID 35958580, 2022). "In rat models, compared with control, IFN-γ and IL-4 levels were elevated post infection, and both decreased to lower levels at week 16 after primary infection." (PMID 36083861, 2022). "Transcriptomics analyses in the hamster model of infection have identified mRNAs for regulatory cytokines (IL-4, IL-10, and IL-21), arginase (Arg1), and low nitric oxide production by macrophages as key factors of immunopathology and parasite persistence." (PMID 35384718, 2022). "Our results highlighted the influence of B cells on host immunity at 24 h after the 1^ dose by the prevalence of IL4-producing B cells (typically present after infection and immunization), whose decay over time is preceded by a significant increase at T1." (PMID 35237261, 2022). "IL-4 promotes the resistance of macrophages to T. cruzi (Tulahuén strain), while in vivo reduced resistance to infection has been described by the same strain." (PMID 36389843, 2022). "Wnt5A treatment prior to infection also correlated with slightly low plasma levels of IL-4, which has been reported to worsen the disease outcome." (PMID 35197983, 2022). "It has been recognized that IL-4 and IL-13 cytokines mediate the goblet cell hyperplasia during the gut infection, which the latter plays a significant protective role against the infection." (PMID 36035429, 2022). "For instance, the interleukin-4 (IL-4) rs2227284 GG genotype in patients with MPP cases has been shown to induce a high burden of infection in children." (PMID 35836993, 2022). "C. sinensis infection caused diminished Th1 cytokines (IL-1β, IL-2, IL-12p70, IFN-γ and TNF-α), Th2 cytokine (IL-4), as well as Th17 cytokine (IL-17A) in sera, which showed decreasing trend by infection intensity." (PMID 36083861, 2022). "The production level of IL-12 and IFN-γ downregulates while the level of IL-4 and IL-10 upregulates during the infection of Leishmania parasites." (PMID 35734580, 2022). "Among Th2 cytokines in the mouse lung, we found that the levels of all four marker cytokines (IL-4, IL-6, IL-10, and IL-13) progressively increased with infection time; similarly, the levels of IL-6, IL-10 and IL-13 were upregulated in the mouse brain." (PMID 35617354, 2022). "Even when using an MOI that was ten times higher, strain CL resulted in low numbers of infected THP-1-derived macrophages, except when cells were stimulated with IL-4 or IL-6, then, both strains presented similar infection rates." (PMID 36389843, 2022). "We found that FXR deficiency in hepatocytes promoted the progression of liver injury, aggravated weight loss and death caused by infection, and promoted inflammatory cytokines production, such as IL-6, IL-1β, TNF-α, IL-4, IL-10, and IL-13." (PMID 35930537, 2022). "In the case of SARS-CoV-2, an increase in the concentration of inflammatory cytokines such as IL-1β, IL-2, IL-6, IL-7 and TNF-α comes to the fore, along with the rise in IL-4 and IL-10 concentrations in a later stage of infection." (PMID 36294388, 2022). "During extracellular pathogen infection, naïve Th cells proliferate and differentiate toward the Th2 subtype, which functions through secreting various effector cytokines, including IL-4, IL-5, IL-6, IL-10, IL-13." (PMID 35241075, 2022).
infection (continued). "In situ studies revealed a profuse recruitment of myeloid cells and of IFNγ- and IL-4-producing T lymphocytes to the site of infection, and the typical histopathological changes induced by dermotropic Leishmania species." (PMID 35770175, 2022). "As a pleiotropic anti-inflammatory cytokine, IL-4 plays an important role in antitumor, anti-infection, and other disease prevention mechanisms." (PMID 35513847, 2022). "A mixed Th1/Th2 immune response (overexpressed IFN-γ, IL-12, IL-2, IL-4, and IL-5) was activated as the infection progressed from 7 to 28 dpi." (PMID 36187827, 2022). "Here, we stimulated healthy skin with IL-4/IL-13 prior to infection to explore the impact of the Th2 cytokine responses on HSV-1 invasion." (PMID 35969080, 2022). "The observation that an intradermal infection with L. major led to an upregulation of IL-4 mRNA at d5 of infection raised the question of the cellular origin of IL-4." (PMID 35894051, 2022). "The IL-4 and IL-13 genes reside only 13 kb apart and coordinate regulation of them determines the typical immune responses observed during infection." (PMID 35745240, 2022). "As infection progressed, these differences became less pronounced at 48 hpi (18-fold; IL-4/13 and 29-fold; TJDP) but still remained significant." (PMID 35456017, 2022). "All tissues showed increased production of IL-4, IL-5 and IL-13 from wk 6, which either peaked at 8-12 wks post infection or remained elevated into chronic stages." (PMID 35958580, 2022). "Th1 cytokines (IL-1β, IL-2, IL-12p70, IFN-γ and TNF-α), Th2 cytokine (IL-4), as well as Th17 cytokine (IL-17A) showed decreasing trend by infection intensity." (PMID 36083861, 2022). "Both Th1 (IFN-γ, TNF-α, IL-12) and Th2 (IL-4 and IL-10) types of cytokines were differentially upregulated during the early stage of infection; however, the Th1 cytokines exhibited stronger activation before 8 hpi compared to those of the Th2 cytokines." (PMID 35215986, 2022). "Given that basophils are important sources of a number of factors that can modulate intestinal permeability, including IL-4 and histamine, we sought to assess the effect of basophil depletion on intestinal permeability following P. y. yoelii 17XNL infection." (PMID 35970557, 2022). "SARS-CoV-2 D614G- and Delta- variant infection induced production of inflammatory cytokines, including high-level of IL-2, GM-CSF, KC at day 3 pi and IL-1β, TNF-α, IL-2, IL-4, IL-6, KC (Neutrophil chemoattractant) at day 7 pi." (PMID 35734088, 2022). "It has been shown that type 2 cytokines IL-4 and IL-13 can increase infection of monocytes and monocyte-derived dendritic cells (MoDCs) by upregulating MMR69,70." (PMID 35869167, 2022). "Levels of IL-4 measured in BALB/c mice at D21 post infection were higher than in C57Bl/6 mice, as has previously been reported." (PMID 36569914, 2022). "Overall, analysis of splenic immune response showed the ratios between IFN-γ/IL-10 and IFN-γ/ IL-4 higher in LmexCen−/− immunized hamsters than in LmexWT infection." (PMID 36463228, 2022). "In this study, we found that IL-4 and IL-5 still had basic expression levels after 20 days of infection." (PMID 35878385, 2022). "Subcutaneous infection of mice with B. malayi induces an early spike in IL-4 in the draining lymph nodes, attributed to NKT cells, which induces alternatively activated macrophages." (PMID 33413609, 2021). "In fact, secretion of cytokines TNF-α and IFN-γ tended to be higher when the host controlled the infection and that of IL-4 and TGF- β when the infection remained uncontrolled." (PMID 33668671, 2021). "These mice also showed a reduced accumulation of neutrophils in the spleen and liver in the chronic phase of infection, and a decreased production of IL-4 and granuloma formation in spleen." (PMID 33816344, 2021). "During infection by these pathogens, IL4 production within the secondary lymphoid organs is restricted to Tfh cells, rather than Th2 cells." (PMID 33912184, 2021).
infection (continued). "At five to six-weeks post infection (the timepoint where egg production begins), they were paired with a naïve KN2 homozygous (IL-4 deficient) male." (PMID 33524040, 2021). "Compared to adults, the number of CD11c+CD11b- AMs that were IL-4+ within the BALF of P. murina-infected neonates was significantly increased at day 41 post-infection." (PMID 34682248, 2021). "Th2 responses can also be induced independently of egg deposition as infection with single sex schistosomes induce pre-patent IL4 production by CD4 T cells." (PMID 33659002, 2021). "Although the piglets were tested only at 28 days post-infection, its lower expression in immunized groups may be involved with an immunosuppressed environment caused by the inhibition of Th1 differentiation, since IL-4 suppresses the production of IFN-γ by Th1 cells." (PMID 34789792, 2021). "C57BL/6 mice infected with the hypervirulent C. neoformans H99 strain showed lower levels of IFN-γ after 14 days of infection, as well as higher levels of IL-17, IL-4 and IL-6 in comparison to uninfected C57BL/6 mice." (PMID 33446850, 2021). "Analysis of proinflammatory cytokine/chemokine profiles during the acute phase of infection between days 14 and 16 post challenge showed marked increases of G-CSF, GM-CSF, IL-1β, IL-4, IL-8, IL-12/23 (p40), IL-18, MCP-1/CCL2, SCD40L, TGF-α, and VEGF." (PMID 34451491, 2021). "CAGE transcriptomics showed up-regulated expression of IL-4i1 in IL-4- or IL-4/IL-13–prestimulated BMDMs 4 hours after infection with HN878 Mtb." (PMID 34739044, 2021). "On day eight post-infection, tamoxifen increased IL-2, IL-4, TNF-α and IFN-γ compared to the same group on day four." (PMID 34204678, 2021). "Our results demonstrate that basophils are the main source of IL-4 in skin superficially infected with S. aureus and that basophil-derived IL-4 dampens the protective IL-17A response against infection." (PMID 34747366, 2021). "Infection with S.tm induced Arg1 expression and IL-4 had an additive effect, whereas IFNγ reduced Arg1 mRNA expression." (PMID 34359992, 2021). "Type 2 cytokines, such as IL-4 and IL-13, trigger a specialized macrophage phenotype; more regulatory and anti-inflammatory macrophages, which is necessary for the adequate infection control." (PMID 34502521, 2021). "Changes in the expression of cytokines IL-10, IL-4, IL-6, IL-1β and TNF-α were measured in BALB/c mice, the susceptible host of S. japonicum, and in M. fortis, the resistant host, before infection and on 3, 7, 10 and 14 dpi, respectively." (PMID 34689797, 2021). "Infection with the nematode N. brasiliensis resulted in an increase in lung Relmα-dtTomato+ interstitial macrophages and eosinophils in an IL-4/IL-13- and STAT6-dependent manner." (PMID 34557875, 2021). "During infection, the generation of Th2 phenotypes, which produce anti-inflammatory cytokines like IL-10, IL-4, TGF-β, is linked to susceptibility whereas induction of pro-inflammatory cytokines producing Th1 phenotypes confers resistance against infection." (PMID 35116028, 2021). "Five genes have been associated with both fibrosis and intensity of infection (RNASE3, IL4, IL10, IFNGI, and IL13)." (PMID 33659002, 2021). "Tfh cells develop as the infection progresses and their IL-4 and IL-21 production regulates different aspects of the GC after soluble extract of Schistosoma mansoni egg-induced type 2 immunization and N. brasiliensis infection." (PMID 33983946, 2021). "Mechanistically, this pointed to early IL-4 signaling instructing DC-derived IL-12 production early after infection, which contributes to the host to control infection." (PMID 35154068, 2021). "IL-4R α2 is also responsible for controlling the IL-4 signaling pathway and averts the progression of infection and inflammation." (PMID 34226412, 2021). "The expression of the two Th2-type cytokines IL-10 and IL-4 in mice was downregulated during the first 10 days post-infection." (PMID 34689797, 2021).